RIPK3 (receptor interacting serine/threonine kinase 3)
Diseases named in the same sentence as RIPK3 in open-access papers (continued):
Sharing a sentence is not in itself a finding about the gene and the disease.
steatosis (14 papers, 2016 to 2026). Increased lipid within the cytoplasm of cells. "For example, inflammation, steatosis, and fibrosis induced in liver by feeding a choline deficient diet was reduced in Ripk3−/− mice." (PMID 39514172, 2024). "ATF3-dependent RIPK3 induction, causing a modal shift of hepatocellular death, can be a therapeutic target for steatosis-induced liver damage, including NASH." (PMID 36690638, 2023). "In alcoholic hepatitis, RIPK3 increases after drinking, whereas RIPK3 deficiency can protect the liver from alcohol‐mediated damage by reducing the steatosis and inflammatory effects of ethanol on liver cells." (PMID 34977874, 2021). "Aged Mlkl−/− and Ripk3−/− mice demonstrated reduced steatosis and liver fibrosis compared to their littermates, suggesting necroptosis-mediated inflammation contributes to age-related MASLD, as chronic inflammation is a known driver of MASH pathology." (PMID 39930289, 2025). "While our findings reveal that the genetic deletion of Mlkl or Ripk3 protects against age-related liver inflammation, steatosis, and fibrosis, the impact on lifespan are more complex." (PMID 39930289, 2025). "H&E staining of liver tissues showed that aging-induced microvesicular steatosis was significantly reduced in both Mlkl−/− and Ripk3−/− old mice." (PMID 39930289, 2025). "Our findings reveal that the genetic deletion of Mlkl or Ripk3 protects mice from age-related hepatic inflammation, steatosis, and fibrosis, hallmarks of MASLD." (PMID 39930289, 2025). "Overexpressing Ripk3 or Mlkl significantly increased steatosis and fibrosis compared to control mice fed the WD." (PMID 39514172, 2024). "Compared with wild-type mice, mice lacking or overexpressing hepatic ATF3 exhibit decreased or increased RIPK3 expression in severe hepatic steatosis and necroptosis after partial hepatectomy." (PMID 38826193, 2024). "Our data show that overexpressing either Ripk3 or Mlkl specifically in the liver induces necroptosis and inflammation in the livers of obese mice that leads to an increase in steatosis, fibrosis, and the incidence of liver tumors." (PMID 39514172, 2024). "Because inflammation plays a role in chronic liver disease and chronic liver disease increases with age, we measured the impact of overexpressing either Ripk3 or Mlkl on steatosis and fibrosis in the old mice." (PMID 37792157, 2023). "We found that the mode of hepatocellular death switches via ATF3-dependent RIPK3 induction from apoptosis to necroptosis with exacerbation of steatosis in obese mice fed a high-fat diet (HFD) after partial fatty liver resection." (PMID 36690638, 2023). "RIPK3–/– mice had less ethanol‐induced steatosis and hepatocyte injury compared to the controls group, but treatment with Nec‐1 did not protect against ethanol‐induced injury." (PMID 34977874, 2021). "RIPK3 global KO mice treated with alcohol had less steatosis, inflammation, and liver injury compared to WT controls." (PMID 33353156, 2020). "The study further compared global RIPK3 KO mice to WT controls and surprisingly found an exacerbation of steatosis, inflammation, liver injury, and hepatocyte apoptosis (positive TUNEL staining) in the RIPK3 KO mice." (PMID 33353156, 2020). "In a methionine choline-deficient (MCD) or choline-deficient high-fat diet (CD-HFD, 35% fat) non-obese model, RIPK3 deletion reduces steatosis, inflammation, and fibrosis." (PMID 38474061, 2024). "However, the role of necroptosis in hepatic steatosis remains controversial because RIPK3 expression is too low to induce necroptosis in the healthy or mild steatotic liver." (PMID 36690638, 2023). "The absence of RIPK3 attenuated cell death, steatosis and mitochondrial ROS production, and RIPK1 deficiency dampened hepatic inflammation after alcohol exposure." (PMID 35083817, 2022).
steatosis (continued). "RIPK3 deficiency exacerbated HFD‐induced apoptosis compared with WT mice, suggesting that inhibition of necroptosis switched cell death from necroptosis to apoptosis, resulting in steatosis and liver injury." (PMID 35083817, 2022). "Therefore, we believe that RIPK3 accumulation following alcohol exposure contributes to cell death and steatosis, and RIPK1 activity is required for alcohol‐induced hepatic inflammation." (PMID 35083817, 2022). "However, in response to 8 weeks of feeding, the lipid droplets of RIPK3−/− mice were small and dispersed, which proved that lack of RIPK3 attenuated steatosis caused by MCD diet in the later stage." (PMID 35083817, 2022). "Therefore, we believed that alcohol‐induced impaired hepatic proteasome function might lead to the hepatic accumulation of RIPK3, contributing to necroptosis and steatosis." (PMID 35083817, 2022). "In our study, we confirm the existence of necroptosis in our in vitro hepatocyte steatosis and hypoxia model as evidenced by alterations in the expression of RIPK1, RIPK3 and MLKL." (PMID 33435617, 2021). "The RIPK3−/− animals had basal insulin resistance, which significantly worsened on a HFD leading to steatosis, inflammation and fibrosis." (PMID 27924226, 2016). "The absence of Mlkl or Ripk3 significantly reduced liver inflammation, steatosis, and fibrosis in aged male mice, supporting the role of necroptosis in age-associated MASLD." (PMID 39930289, 2025). "Nevertheless, studies investigating the consequences of inhibiting necroptosis through targeting either RIPK3 or MLKL in mice have presented contradictory outcomes concerning inflammation, steatosis, and fibrosis, with the observed effects varying based on the dietary conditions." (PMID 38474061, 2024). "The frequency of either ATF3+ or RIPK3+ hepatocytes increased in accordance with an increase in the scores of ballooning, but not that of steatosis." (PMID 36690638, 2023).
Arthritis (13 papers, 2015 to 2025). Inflammation of a joint. "Global loss of RIPK3 in both caspase-8 deletion constructs causes the response to arthritis to revert back to control levels via a mechanism potentially independent of cell death." (PMID 28978351, 2017). "RIPK3 deletion reversed joint dysregulation induced by caspase-8 deficiency under arthritic conditions and may have an inhibitory effect on arthritis induced by the transfer of K/BxN serum." (PMID 38684668, 2024). "Interestingly, this latter finding contrasts the previously reported acceleration of resolution phase of arthritis caused by the Ripk3 deficiency in the KRN-serum transfer arthritis model." (PMID 29434332, 2018). "However, we observed that global deletion of RIPK3 in CreLysMCasp8flox/flox and CreCD11cCasp8flox/flox mice causes the response to K/BxN serum-transfer-induced arthritis to revert to that of Casp8flox/flox control mice, indicating that the aberrant responses observed require RIPK3 action." (PMID 28978351, 2017). "In vivo, pharmacological inhibition of ASIC1a or RIPK3, as well as RIPK3 knockdown, significantly alleviated arthritis progression in CIA and CAIA mouse models." (PMID 40963902, 2025). "As expected, inhibition of ASIC1a and RIPK3 significantly attenuated arthritis development in the CIA model." (PMID 40963902, 2025). "To investigate the regulatory roles of ASIC1a and RIPK3 in arthritis, we treated CIA mice with the ASIC1a-specific inhibitor PcTX1, the non-specific inhibitor Amiloride, and the RIPK3-specific inhibitor GSK872." (PMID 40963902, 2025). "Global deletion of RIPK3 in CreLysMCasp8flox/flox mice was sufficient to restore the inflammatory response to K/BxN serum-transfer-induced arthritis to that of the control Casp8flox/flox mice." (PMID 28978351, 2017). "Further, we included analysis of K/BxN serum-transfer-induced arthritis in B6, RIPK3–/– and RIPK3–/–Casp8flox/flox control mice." (PMID 28978351, 2017). "Deletion of RIPK3 in CreCD11cCasp8flox/flox mice reversed the response to K/BxN serum-transfer-induced arthritis to levels below that of Casp8flox/flox mice." (PMID 28978351, 2017). "The arthritis score in RIPK3-/- mice was notably lower than in wild-type CAIA mice." (PMID 40963902, 2025). "RIPK3 signaling plays an important role in the dysregulation of immune responses to arthritis induced by the transfer of K/BxN serum (serum from mouse models of severe arthritis) in mice." (PMID 38684668, 2024). "In the context of hTNFTg arthritis, complete absence of Ripk3 kinase does not affect development of arthritis, indicating that Ripk3-mediated signals are not directly implicated in the pathology." (PMID 39122678, 2024). "RIPK3 in IAP-deficient mice promotes autoantibody-mediated arthritis by promoting NLRP3 inflammasome formation and IL-1β release, which may be a consequence of RIPK3 inhibition of necroptosis by shifting the form of cell death to pyroptosis." (PMID 35464445, 2022). "The absence of any effect of Ripk3 deficiency in the development of arthritis in hTNFtg mice indicated that Ripk3-mediated signals are dispensable for the arthritogenic behaviour of hTNFTg SFs in vivo." (PMID 29434332, 2018). "Moreover, Ripk3 is dispensable for TNF-mediated arthritis, yet it is required for synovitis in mice with mesenchymal-specific IKK2 deletion." (PMID 29434332, 2018). "Collectively, these findings exclude a direct role of Ripk3 involvement in TNF-mediated arthritis." (PMID 29434332, 2018). "We did find that RIPK3–/–Casp8flox/flox mice have slower induction of arthritis than RIPK3–/– mice, potentially owing to interactions from the remaining 129 background present in both Casp8flox/flox and RIPK3–/– strains despite being backcrossed to B6 for over 12 and 4 generations, respectively." (PMID 28978351, 2017). "Considering IAPs regulate RIPK3 activity, and suppress K/B × N arthritis severity, we sought to determine if a TLR–TRIF–RIPK3 axis could regulate K/B × N arthritis via caspase-8 or MLKL signalling." (PMID 25693118, 2015).
Arthritis (continued). "Caspase-8 is an endogenous suppressor of RIPK signaling; therefore, we examined whether unchecked RIPK3 signaling may contribute to the aberrant responses to K/BxN serum-transfer-induced arthritis observed in our CreLysMCasp8flox/flox and CreCD11cCasp8flox/flox caspase-8-deficient mice." (PMID 28978351, 2017). "Therefore, for optimal therapeutic targeting of RIPK3 in inflammatory diseases, such as arthritis, it will be important to carefully evaluate the bifurcation of RIPK3-induced necroptosis and DAMP-driven inflammation versus cell intrinsic-induced cytokine production and activation." (PMID 25693118, 2015). "Genetic ablation of Ripk3 or Mlkl, or inhibition of RIPK1 kinase activity, significantly attenuates arthritis severity in A20myel-KO mice." (PMID 41583484, 2025). "Pharmacological inhibitors of ASIC1a (PcTX1) and RIPK3 (GSK-872) were employed to evaluate their therapeutic effects on migration and invasion in vitro and arthritis progression in vivo using the collagen-induced arthritis (CIA) model." (PMID 40963902, 2025). "Next, we similarly investigated a role of Ripk3 in CD4+ T cell homeostasis and the SKG arthritis model." (PMID 34548542, 2021). "Gsdmd−/−, Ripk3−/−, or Gsdmd−/−Ripk3−/− SKG mice showed severe arthritis with expansion of arthritogenic Th17 cells in the draining LNs and inflamed joints, which was comparable to that in wild-type SKG mice." (PMID 34548542, 2021). "Here we show the role of the p55TNFR–IKK2l–Ripk3 axis in the regulation of synovial fibroblast homeostasis and pathogenesis in TNF-mediated mouse models of arthritis." (PMID 29434332, 2018). "Here we dissect the requirement for mesenchymal p55TNFR and IKK2/Ripk3 in models of acute and chronic TNF-mediated arthritis and investigate their function in arthritic SFs." (PMID 29434332, 2018). "Here the authors dissect TNF-induced death and activation signalling in RA synovial fibroblasts and TNF-driven arthritis and indicate that a successful therapeutic strategy might be to target both IKK2 and RIPK3 at the same time." (PMID 29434332, 2018). "Consistent with in vitro experiments, interleukin-1 (IL-1)-dependent autoantibody-mediated arthritis is exacerbated in mice lacking IAPs, and is reduced by deletion of RIPK3, but not MLKL." (PMID 25693118, 2015). "Collectively, these data document substantial in vivo evidence that the clinical chronicity of K/B × N arthritis is dependent on a TLR–TRIF–RIPK3–IL-1β axis that occurs independent of the RIPK3 substrate and essential necroptotic effector, MLKL." (PMID 25693118, 2015). "Although dependent on RIPK3, this mechanism occurs independent of necroptosis, since MLKL deficiency did not alter arthritis pathogenesis." (PMID 25693118, 2015). "Since caspase-8 may mediate its suppressive effect during K/BxN serum-transfer-induced arthritis independent of preventing RIPK3-mediated necroptosis, we sought to determine alternate modalities by which this RIPK3-mediated suppression potentially occurs." (PMID 28978351, 2017). "While a recent report shows that RIPK3–/– mice display more rapid resolution of K/BxN serum-transfer-induced arthritis compared to control mice, we did not observe this pattern in our study, which may be the result of K/BxN serum differences, colony environment and/or diet." (PMID 28978351, 2017).
prostate carcinoma (13 papers, 2014 to 2025). A carcinoma that arises from epithelial cells of the prostate gland. "It is reported that SIRT3 inhibited RIPK3‐mediated necroptosis and innate immunity, promoting prostate cancer progression." (PMID 39501597, 2024). "In conclusion, IDOAMP directly inhibited Aurora kinase A and promoted the RIPK1/RIPK3/MLKL necrosome activation to inhibit the prostate cancer." (PMID 35965682, 2022). "In advanced prostate cancer, RIPK3 is significantly suppressed at a rate proportional to tumor size and prostate-specific antigen (PSA)." (PMID 34869390, 2021). "For example, RIPK3 inhibits prostate cancer progression by activating MLKL through phosphorylation and necroptosis activation." (PMID 34869390, 2021). "RIPK3 expression is significantly decreased in prostate cancer compared with that in normal tissues, and its overexpression significantly inhibits the proliferation and invasion of prostate cancer in vitro and in vivo." (PMID 34869390, 2021). "Mechanistically, we found that SIRT3 and SIRT6 promote prostate cancer progress by inhibiting RIPK3-mediated necroptosis and innate immune response." (PMID 33282964, 2020). "Interestingly, RIPK3 has been shown to be downregulated in prostate cancer, and its overexpression suppressed prostate cancer cell migration and invasion." (PMID 35008216, 2021). "In the Atg5-deficient prostate cancer cell line DU-145, sorafenib could mediate necroptosis by inducing the RIPK1/RIPK3/MLKL pathway, and this process can be blocked by the RIPK1 inhibitor Nec-1." (PMID 34869390, 2021). "However, it is still unclear how SIRT3 and SIRT6 regulate RIPK1/RIPK3-mediated necroptosis and in turn maintain prostate cancer progress." (PMID 33282964, 2020). "Castration-resistant prostate cancer cells treated with metformin and simvastatin were shown to induce Ripk1- and Ripk3-dependent necrosis, suggesting that these necroptosis molecules may be important in the antitumor effects mediated by metformin." (PMID 29899823, 2018). "Up-regulated RIPK3 can remain active in the RIPK3/MLKL signaling pathway and induce necroptosis to alleviate the progression of prostate cancer." (PMID 36611858, 2022).
renal fibrosis (13 papers, 2018 to 2025). A final common manifestation of a wide variety of chronic kidney diseases characterized by glomerulosclerosis and tubulointerstitial fibrosis. "It is reported that RIPK3 inhibition or RIPK3 deficiency attenuates renal fibrosis via the regulation of the NLRP3 inflammasome in a mouse model of FA nephropathy." (PMID 35924048, 2022). "We found that RIPK3 deficiency attenuated diabetes-induced renal fibrosis, in association with reduced activation of the NLRP3 inflammasome." (PMID 32591618, 2020). "It has been recently being independently reported that RIPK3 is implicated in renal fibrogenesis in two alternative models of renal fibrosis ie the unilateral ureteral obstruction (UUO) and adenine-induced models of CKD5." (PMID 32591618, 2020). "Thus, BM-derived cells with Ripk3 deficiency alleviated the inflammasome activation and renal fibrosis during the development of IRI to CKD." (PMID 30158627, 2018). "The recent studies further suggested that RIPK3 is involved in the development of renal fibrosis, brain injury after subarachnoid hemorrhage, and lung injury by activating the NLRP3 inflammasome." (PMID 35514432, 2022). "RIPK3 exacerbates renal fibrosis specifically via the PI3K/AKT-dependent activation of metabolic enzyme ATP citrate lyase (ACL)." (PMID 36361505, 2022). "We discuss here the biological functions of RIPK3 and its role in the development of renal fibrosis." (PMID 32613000, 2020). "In this study, we examined the role of RIPK3 in DKD induced renal fibrosis using a streptozotocin (STZ)-induced diabetic mouse model." (PMID 32591618, 2020). "The protein kinase RIPK3 is involved innecroptosis; however, recent evidence indicates that it also has non-canonicalfunctions, including its involvement in the development of renal fibrosis." (PMID 38234604, 2023). "In contrast, another study demonstrated that RIPK3 deficiency in the same UUO model prevents renal fibrosis without altering the mRNA expression of interleukin (IL)-1β, tumor necrosis factor (TNF)-α, and TGF-β1." (PMID 32613000, 2020). "In contrast, the mice with Ripk3−/− background, showed significantly reduced levels of renal fibrosis and inflammasome activation than the mice with WT background, irrespective of whether they were transplanted with Ripk3+/+or Ripk3−/− bone marrow." (PMID 30158627, 2018). "Ripk3−/− to Ripk3+/+chimeric mice reduced renal fibrosis and inflammasome activation." (PMID 30158627, 2018). "Here we found that deletion of RIPK3 or MLKL alleviated the NLRP3 inflammasome activation and IL-1β release in kidney after IRI corresponding with the reduction of renal fibrosis." (PMID 30158627, 2018). "Collectively, these data indicated that both RIPK3 and MLKL contributed to progression of renal fibrosis post IRI." (PMID 30158627, 2018). "Furthermore, we found that treatment with RIPK1 inhibitor, Nec-1 significantly inhibited the activation of the RIPK1/RIPK3/MLKL signaling pathway, ameliorated renal dysfunction, and reduced kidney inflammation and renal fibrosis." (PMID 36756299, 2023). "The role of RIPK3 in diabetic kidney disease (DKD) induced renal fibrosis has not been previously determined." (PMID 32591618, 2020). "AKF-PD and Nec-1 exert effective activity against renal fibrosis, and AKF-PD may inhibit inflammation through RIPK3-mediated necroptosis." (PMID 33390935, 2020). "Moreover, in UUO and AD fibrosis models, renal fibrosis was reduced, while renal function was improved in RIPK3−/−, but not in MLKL−/− mice versus WT mice." (PMID 36361505, 2022). "Interestingly, there is no statistical significance in renal fibrosis among these Ripk3−/−, Mlkl−/− and Ripk3−/−Mlkl−/− mice with the same period of renal ischemia." (PMID 30158627, 2018).